CRP (C-reactive protein)
Diseases named in the same sentence as CRP in open-access papers (continued):
Sharing a sentence is not in itself a finding about the gene and the disease.
atherosclerosis (continued). "Many of the metabolites that were correlated with inflammation, as measured by serum CRP levels, are associated with lipid metabolism and may contribute to the increased levels of atherosclerosis associated with inflammatory disease." (PMID 23740368, 2013). "Airway inflammation may induce systemic inflammation, particularly C-reactive protein (CRP) production, which is also associated with the progression of atherosclerosis." (PMID 24040911, 2013). "CRP, in turn, has been implicated directly in atherosclerosis and its complications." (PMID 24321217, 2013). "Although there is apparent argument regarding the role of CRP in the risk of atherosclerosis, the positive results support the need to explore the exact mechanisms by which CRP might trigger the development of atherosclerotic lesions." (PMID 23162475, 2012). "There is considerable interest in whether CRP has a causal role in CHD whether CRP is merely a marker of underlying atherosclerosis." (PMID 23162475, 2012). "OSA has also been associated with systemic inflammation, reflected by increases in C-reactive protein and serum amyloid A levels, which may advance atherosclerosis and is associated with increased cardiovascular risk." (PMID 22655109, 2012). "CRP may reflect a greater burden of atherosclerosis or alternatively may identify a high-risk atherosclerosis phenotype with an active inflammation and atherosclerotic plaque that is vulnerable to rupture." (PMID 22963582, 2012). "Although CRP can merely be a marker of an underlying inflammatory process, it is possible that CRP may be directly involved in the pathogenesis of inflammation/atherosclerosis." (PMID 22701277, 2012). "In our setting, hs-CRP may be useful marker to assess early atherosclerosis and cardiovascular risk, particularly in those children with normal BMI." (PMID 29062730, 2012). "Despite this, it continues to be debated whether CRP plays a causal role in the development of atherosclerosis, or is simply an important clinical marker of inflammation and cardiovascular risk." (PMID 23162475, 2012). "A number of potential mechanisms by which CRP may play a causal role in atherosclerosis and CV disease have been implicated, including recruitment of monocytes to the atherosclerotic lesion, intimal growth, and endothelial dysfunction." (PMID 22208681, 2011). "With prevalent CVD, CRP may be a by-product of atherosclerosis and its association could result from reverse causation; our study could not demonstrate this as our RA patients had not experienced incident CVD." (PMID 20436910, 2010). "However, it is also possible that CRP is produced by inflammation within atherosclerotic plaque and therefore associates with atherosclerosis by reverse causality." (PMID 20436910, 2010). "C-reactive protein (CRP), a biomarker of systemic inflammation, independently associates with endothelial dysfunction, subclinical atherosclerosis and arteriosclerosis and clinical manifestations of atherosclerosis in the general population." (PMID 20436910, 2010). "Therefore, the role of CRP as causal factor in the development of atherosclerosis remains controversial." (PMID 20920173, 2010). "Furthermore, it is associated with inflammatory state (CRP) and endothelial damage (sE-selectin), underlining the early development of atherosclerosis in overweight teenagers and the connecting role of inflammation mediated by factors such as IL-18." (PMID 20169140, 2010). "Whether CRP is causally implicated in atherogenesis or is the results of atherosclerosis is disputed." (PMID 20436910, 2010). "Additionally, there is increasing evidence that some of the classical risk factors for atherosclerosis also have independent genetic components [lipids, BMI, BP, lipoprotein(a), homocysteine, type 2 diabetes, fibrinogen, C-reactive protein (CRP)]10." (PMID 21150009, 2010). "Therefore, in addition to acting as a biomarker, CRP plays a causal role in the development of atherosclerosis and thrombosis." (PMID 19240794, 2009).
atherosclerosis (continued). "On the contrary, adults with Down syndrome seem to be protected against atherosclerosis, despite having elevated risk factors, such as elevated total body fat, higher levels of triglycerides and C-reactive protein, and lower levels of moderate to vigorous physical activity." (PMID 19844572, 2009). "Inflammation is a prominent feature of atherosclerosis, and it is postulated that as an acute-phase protein, elevation of plasma CRP may signal the underlying atherosclerotic process." (PMID 19804641, 2009). "In this study, CRP expression coincided with the remodeling process and with bronchial wall inflammation as it has previously been reported to associate with the progression of atherosclerosis in coronary arteries." (PMID 19503785, 2009). "Mechanisms, in support of such a notion include the acceleration of the progression of atherosclerosis in apolipoprotein E-deficient mice, suggesting direct involvement of CRP in atherogenesis, and its presence in atherosclerotic lesions but not in the normal vessel wall." (PMID 19480687, 2009). "Interestingly there is a recent publication reporting that C-reactive protein (CRP), a suggested independent risk marker of atherosclerosis, induces VEGF expression via Erk/PI3K signalling." (PMID 19040724, 2008). "A Swedish cross-sectional study that investigated the relationship between CRP, sub-clinical atherosclerosis and various cardiovascular risk factors found CS consumption to be the variable that showed the strongest association with CRP levels (Hulthe and others, 2001)." (PMID 19578488, 2008). "However, much larger analyses using the genetic approach we and others have described, as well as intervention studies involving a new, specific CRP-inhibitor are needed to more definitively assess the potential causal role for CRP in atherosclerosis and CHD." (PMID 18714381, 2008). "Thus, use of gene variants as an unconfounded instrument for CRP levels offers the opportunity of assessing the causal relevance of CRP for atherosclerosis." (PMID 18714381, 2008). "SM might be a marker for an inflammatory effect, and inflammatory markers such as CRP have been shown to be important risk factors for atherosclerosis." (PMID 16396678, 2006). "It has even been suggested that RA and atherosclerosis may share a common predisposition factor; CRP is the common denominator for both diseases." (PMID 16646989, 2006). "However, it is still debated whether CRP has a direct causal relationship with progression of atherosclerosis, or if the increase in plasma CRP is a response to the inflammatory processes involved in atherosclerotic CAD." (PMID 40309624, 2025). "We verified the existence of a negative association between C-reactive protein and amyloidosis and a positive association between C-reactive protein and atherosclerosis by Mendelian randomization, which may provide some reference value for subsequent studies and treatment in the clinic." (PMID 40779499, 2025). "Finally, TJA may reduce systemic inflammation by eliminating the inflamed joint, decreasing cytokines like IL-6, TNF-α, and CRP, which are linked to endothelial dysfunction and atherosclerosis." (PMID 40688840, 2025). "Elevated levels of CRP not only indicate the presence of an inflammatory state in the body but also directly participate in the inflammatory response, damaging vascular endothelial cells and promoting the onset and progression of atherosclerosis, thereby increasing the risk of myocardial injury." (PMID 41341827, 2025). "In addition to its role as a marker of systemic inflammation, CRP may be a causative factor of vascular inflammation in atherosclerosis." (PMID 38753254, 2024). "In agreement with our results, the Multi-Ethnic Study of Atherosclerosis showed that adherence to a dietary pattern containing a high amount of whole grains and a low amount of sodium was inversely associated with serum concentrations of CRP, IL-6, and homocysteine." (PMID 37496018, 2023).
atherosclerosis (continued). "In addition, CRP levels have a known association with atherosclerosis and other large-artery-related pathology, which not only shares a vascular risk factor profile overlap with SVD, but might also chronically exert effects on the microvasculature." (PMID 37685924, 2023). "In addition to the effects on lesion size, lipid profile, and oxidation, curcumin also affects inflammation, another hallmark of atherosclerosis, by reducing systemic levels of inflammatory cytokines such as IL-6, Tumor necrosis factor-alpha (TNFα), and C-reactive protein (CRP)." (PMID 35159155, 2022). "This suggests that using CRP as a biomarker to identify people who may benefit from potent anti-inflammatory therapies also selects a population at increased risk of fatal infection, in keeping with recent clinical trial data in people with atherosclerosis." (PMID 35535512, 2022). "Since it is an indicator of systemic inflammation, CRP may predict the burden of atherosclerosis and has a predictive and diagnostic role in different types of stroke, such as ischemic stroke and fatal stroke, but the role of CRP in predicting hemorrhage stroke outcome was even less clear." (PMID 36262245, 2022). "CRP concentration reflects inflammation that is implicated in post-infarct myocardial injury and repair as well as other processes triggered by acute MI such as accelerated atherosclerosis and endothelial dysfunction, all of which can be involved in the pathophysiology of HF." (PMID 33804661, 2021). "CRP is the most commonly used inflammatory marker in clinical practice, and its importance not only lies in its reliability but also, along with some other acute-phase reactants, in its ability to be an active part of the pathogenic mechanism of atherosclerosis." (PMID 31939522, 2020). "Therefore, the found association of factor H Y402H polymorphism with AMD, DDD and possibly also with atherosclerosis and Alzheimer’s disease could be related to the reduced binding of 402H to CRP and oxidized lipids compared to 402Y." (PMID 33363547, 2020). "Therefore, it is of considerable importance to clarify whether CRP plays a causative role in atherosclerosis and if so, whether it could represent an interesting novel target for intervention." (PMID 31151201, 2019). "Therefore, we suggest that B. angulata WF may be useful for the therapeutic treatment of CRP-associated atherosclerosis." (PMID 30524759, 2018). "Analyzing circulating levels of such complement components demonstrated that patients with advanced atherosclerosis present with elevated levels of anaphylatoxin C5a, predictive of major cardiovascular events and independent of known risk markers such as C reactive protein (CRP) or fibrinogen." (PMID 25784879, 2015). "Our work indicates that CX3CL1 and GM-CSF may represent putative biomarkers of inflammation associated with atherosclerosis, such as C-reactive protein, but are mechanistically tied to atherosclerosis based on the well established findings in animal models of atherosclerosis." (PMID 24995121, 2014). "This mirrors the argument applied to conventional laboratory risk factors, such as C-reactive protein (CRP), which also fail to identify premature atherosclerosis in patients with SLE as they may be elevated due to the disease itself or infective complications." (PMID 24171119, 2013). "Atherosclerosis is a chronic inflammatory disease characterized by inflammation both in the arterial wall and systemically in the body, and atherothrombotic disease is associated with increased inflammation as exemplified by elevated levels of C-reactive protein." (PMID 23457642, 2013). "CRP may be used as a predictor of cardiovascular disease based on its correlation with the other known cardiac risk factors and their role in the formation of atherosclerosis." (PMID 22834788, 2012).
atherosclerosis (continued). "Moreover, it has been proposed that leptin plays a pathogenic role in atheromatous plaques, due to its positive association with C-reactive protein (CRP) and soluble IL-6 receptor (sIL-6R), two inflammatory mediators involved in the pathogenesis of atherosclerosis." (PMID 22910888, 2012). "High sensitivity CRP may reflect an exaggerated inflammatory response associated with traditional CV risk factors or reflect the causal role of inflammation in the initiation and/or progression of atherosclerosis, further observations are needed." (PMID 22208681, 2011). "Thus, homocysteine and CRP appear to act not only as markers of cardiovascular risk, but based on in vitro studies, to induce inflammatory responses and thus perhaps play a direct role in the pathogenesis of atherosclerosis." (PMID 20157364, 2008). "Thus, considering the possibility that CRP and endotoxin are both risk factors for atherosclerosis and may act synergistically in vitro and in vivo, our strategy was not to remove the endotoxin present in CRP but to measure the concentrations present." (PMID 20157364, 2008). "Circulating CRP concentration has been shown to be predictive of future cardiovascular disease risk in prospective studies among asymptomatic individuals and may have a direct effect on the progression of atherosclerosis." (PMID 17958896, 2007). "Among those who did, imaging-based evaluation of subclinical atherosclerosis was the most frequently selected approach, followed by Lp(a) and triglycerides, hs-CRP, and apoB." (PMID 42279067, 2026). "This paradoxical finding is novel and warrants further longer‐term follow‐up, given that elevated CRP is a biomarker of vascular inflammation and a predictor of adult‐onset atherosclerosis and cardiovascular disease." (PMID 41231203, 2026). "Specifically, vitamin D reduces the expression of pro-inflammatory cytokines, leading to decreased CRP levels and limiting macrophage-derived foam cell formation, a critical step in atherosclerosis progression." (PMID 41597410, 2026). "CRP can directly participate in atherosclerosis development through mechanisms such as activating the complement system, promoting monocyte adhesion and chemotaxis, and inducing endothelial cell expression of adhesion molecules." (PMID 41607462, 2026). "CRP involvement in atherosclerosis is due to nitric oxide inhibition in cardiovascular endothelial cells." (PMID 40137085, 2025). "Pro-inflammatory mediators (IL6, TNF-α, and CRP) driven by periodontal disease are also known promoters of endothelial dysfunction, atherosclerosis, and destabilization of atherosclerotic plaque." (PMID 41011105, 2025). "Chronic systemic inflammation in psoriasis patients is associated with heightened levels of inflammatory markers, including C-reactive protein (CRP), and an augmented risk of atherosclerosis and myocardial infarction." (PMID 40560394, 2025). "IL-6, which is mostly secreted by T cells and macrophages, promotes atheroprogression, plaque instability, and the generation of C-reactive protein (CRP), all of which are factors in the onset and advancement of clinical atherosclerosis." (PMID 40218291, 2025). "After 12 months of JAKi therapy, there was a significant reduction in systemic inflammation, illustrated by a drop in CRP, along with stabilization of surrogate markers of subclinical atherosclerosis." (PMID 40649049, 2025). "Clinically, periodontitis is associated with increased levels of systemic markers, such as CRP and increased carotid intima-media thickness, indicative of atherosclerosis." (PMID 40076622, 2025). "IL-6 is involved in the activation of acute-phase proteins, such as C-reactive protein (CRP), and has been shown to promote endothelial dysfunction, which is a critical step in the development of atherosclerosis." (PMID 41515595, 2025).
atherosclerosis (continued). "They inhibit the expression of pro-inflammatory cytokines such as IL-6, TNF-α, and C-reactive protein (CRP), which are directly implicated in the pathogenesis of atherosclerosis." (PMID 40807170, 2025). "Since serum IL‐6 and CRP are predictors of atherosclerosis progression, we found the effects of OO and OA on IL‐6 and CRP were uncertain in our umbrella review." (PMID 41142012, 2025). "C-reactive protein (CRP) itself is an acute phase reactant which can contribute to the process of atherosclerosis." (PMID 40863571, 2025). "Research on the progression of atherosclerosis has indicated that ascending levels of inflammatory factors such as CRP and interleukin 6 play a role in chronic inflammation during the process of atherosclerosis formation." (PMID 39949401, 2025). "Chronic periodontal inflammation contributes to endothelial dysfunction and promotes systemic atherosclerosis via cytokine release (IL-6, CRP) and microbial dissemination." (PMID 41303261, 2025). "C-reactive protein (CRP) indicates systemic inflammatory response and has been linked to the pathological progression of atherosclerosis and other inflammatory diseases." (PMID 39932324, 2025). "Beyond CRP and eGFR, disorders of lipid metabolism and atherosclerosis emerged as significant predictors of periodontal disease." (PMID 39859455, 2025). "CRP has established itself as a reliable, accessible, and independent predictor of vascular health and atherosclerosis progression." (PMID 40725102, 2025). "CRP is an indicator of acute-phase inflammation and a mediator of atherosclerosis stimulating expression of adhesion molecules and inflammatory cells." (PMID 40667402, 2025). "LDL and C-reactive protein (CRP) lipid distribution in atherosclerosis were improved by liraglutide with metformin in newly diagnosed diabetic patients following standard statin therapy." (PMID 40708853, 2025). "CRP has been demonstrated to play a pivotal role in the progression of atherosclerosis, from its initial stages." (PMID 39941605, 2025). "Studies have demonstrated a close relationship between elevated CRP levels and increased risks of atherosclerosis, myocardial infarction, and other cardiovascular events." (PMID 40937117, 2025). "Hypersensitive C-reactive protein (hs-CRP), a critical marker of inflammation, plays a significant role in atherosclerosis intensified by HHcy." (PMID 39898976, 2025). "CRP is a highly sensitive protein found in the blood due to inflammation, leading to an increased possibility of cardiovascular disease and atherosclerosis." (PMID 40244195, 2025). "It activates hepatic cells to produce C-reactive protein, thereby promoting inflammation, enhancing platelet adhesion, and facilitating the development of atherosclerosis." (PMID 40600192, 2025). "Simultaneously, inflammatory markers like C-reactive protein and interleukin-6 accelerate atherosclerosis by increasing endothelial dysfunction, lipid deposition, and vascular calcification." (PMID 40011291, 2025). "Animal models of atherosclerosis (AS) further demonstrate the role of T. forsythia and its protein BspA in promoting plaque enlargement, increasing serum CRP and LDL levels, and decreasing HDL levels." (PMID 40136726, 2025). "IL-6 is a potent stimulator of CRP production, produced by vascular smooth muscle cells in reaction to atherosclerosis." (PMID 40933377, 2025). "Inflammation is a key driver of atherosclerosis, with CRP, IL-6, and TNF-α serving as markers of disease activity." (PMID 40217801, 2025). "This inflammation leads to an elevation of proinflammatory cytokines, such as interleukin-6 and C-reactive protein, which disrupt endothelial function and promote atherosclerosis." (PMID 40708645, 2025). "Some studies have reported increases in inflammatory markers such as CRP, potentially favoring the development of atherosclerosis." (PMID 41010495, 2025).